PVALB (parvalbumin)
Diseases named in the same sentence as PVALB in open-access papers (continued):
Sharing a sentence is not in itself a finding about the gene and the disease.
schizophrenia (continued). "Deficit of parvalbumin-expressing interneurons is an accepted feature in schizophrenia, also demonstrable in animal models." (PMID 23150836, 2012). "The expression levels of parvalbumin and somatostatin have previously been reported to be reduced in patients with schizophrenia in the TRC collection." (PMID 22545112, 2012). "For instance, in situ hybridization in post-mortem brains of individuals with schizophrenia showed that parvalbumin-positive interneurons were still present in the same numbers but that levels of parvalbumin mRNA per cell were markedly reduced." (PMID 22936973, 2012). "A decrease in parvalbumin-positive interneurons has also been shown in several animal models of schizophrenia including in prefrontal cortex and hippocampus after a late pregnancy (gestational day 17) prenatal immune challenge." (PMID 22238649, 2012). "Convergent evidence shows that parvalbumin-positive FS play a pivotal role in the cognitive impairments seen in schizophrenia." (PMID 22815864, 2012). "For example, the mRNAs encoding parvalbumin (PV) and somatostatin (SST), each of which is expressed in a separate subset of cortical GABA neurons, are decreased in schizophrenia." (PMID 22937123, 2012). "Analyses suggested that gene expression changes in autism, schizophrenia, and bipolar disorder were consistent with an immature developmental gene expression program of parvalbumin-positive fast-spiking interneurons (FS cells)." (PMID 22936973, 2012). "The number of parvalbumin-positive interneurons decreases in the hippocampi of patients with schizophrenia, possibly because of excitotoxic damage, which has been linked to NMDA receptor dysfunction." (PMID 22815864, 2012). "When these markers were entered as covariates into multiple regression models, the relationship between the FS cell index and parvalbumin remained significant in all cases (autism: p<0.0001; schizophrenia: p<0.02; bipolar: p<0.0002)." (PMID 22936973, 2012). "Reduced expression of parvalbumin, a marker of mature FS cells, has been reported in individuals with schizophrenia and bipolar disorder and in mouse models of schizophrenia and autism." (PMID 22936973, 2012). "Schizophrenia subjects show a decrease in Cnr1 mRNA and protein levels in the prefrontal cortex, as well as diminished parvalbumin mRNA in the same region." (PMID 22103416, 2011). "Previous studies have reported that changes in parvalbumin-expressing GABAergic neurons are important in the pathology of schizophrenia and autism (see Discussion)." (PMID 21437241, 2011). "Previous studies have indicated that chronic stress, a significant factor in the onset of depression, can increase synaptic inhibition mediated by PV-Ins and reduce the expression of parvalbumin and somatostatin in postmortem tissue from schizophrenia patients." (PMID 40931040, 2026). "Likewise, decreased levels of GAD67 mRNA and protein are consistently reported in the postmortem brains of schizophrenia patients, with the reduction being most pronounced in parvalbumin-positive interneurons, suggesting a functional impairment in these cells." (PMID 40711497, 2025). "Maintaining and retrieving memories despite the presence of distractions or interference from similar memories requires appropriate attentional focus in a process that involves the prefrontal cortex (PFC), an area with known parvalbumin (PV) impairments in patients with schizophrenia." (PMID 41234277, 2025). "This was achieved by reducing the increase in 8-oxo-dG-positive cells (a marker of oxidative DNA damage) and preventing the decrease in parvalbumin-positive cells (GABAergic inhibitory neurons that express parvalbumin and play a role in cognitive impairment in schizophrenia) in mPFC and hippocampus." (PMID 40722922, 2025).
schizophrenia (continued). "Collectively, these results highlight the therapeutic potential of 5-HT4R activation in pyramidal, parvalbumin+, and somatostatin+ neurons of hippocampal–prefrontal pathways for mitigation of cognitive and negative symptoms associated with schizophrenia." (PMID 40332153, 2025). "While the number or density of parvalbumin-positive interneurons seems to be unaffected, the mRNA expression levels were decreased in schizophrenia patient samples compared to the controls, possibly hinting at alterations in the plasticity (and activity) of PV-interneurons." (PMID 40374740, 2025). "Precisely because parvalbumin loss does not inherently indicate a reduction in subsets of GABAergic neurons, we cannot directly link parvalbumin loss to epilepsy and schizophrenia." (PMID 39858450, 2025). "Such novel medications may offer an alternative approach to managing the symptoms of schizophrenia, including psychosis and, preferably, cognitive impairment, through the restoration of the firing of parvalbumin neurons." (PMID 39201380, 2024). "In this context, the GABA hypothesis of schizophrenia offers a promising avenue for the development of novel biomarker-driven therapeutics by targeting the dysfunction of parvalbumin neurons." (PMID 39201380, 2024). "Selective vulnerability of parvalbumin-positive interneurons is known to occur under different experimental conditions, such as epilepsy, interleukine 6 overexpression, and the ketamine schizophrenia model." (PMID 39200191, 2024). "Electroencephalography and magnetoencephalography studies have demonstrated impairments in evoked gamma oscillations in patients with schizophrenia, which may reflect the dysfunction of cortical parvalbumin neurons." (PMID 39201380, 2024). "Furthermore, the gamma-band ASSR is considered to reflect parvalbumin-positive GABAergic interneuron function and is reduced in patients with schizophrenia, reflecting dysfunction of GABAergic interneurons." (PMID 38472253, 2024). "However, biomarkers that capture the dysfunction of parvalbumin neurons are required for these modulators to be effective in the pharmacotherapy of schizophrenia." (PMID 39201380, 2024). "Furthermore, studies using animal model relevant to schizophrenia have also indicated that altered N-methyl-D-aspartate (NMDA) receptor signaling onto parvalbumin-positive interneurons results in gamma oscillation deficits in cortical microcircuits." (PMID 38472253, 2024). "Moreover, the distribution of IDAC alterations in patients with schizophrenia is consistent with the cortical distribution of parvalbumin and somatostatin GABA interneurons, further supporting the evidence of a deficient GABA system in this disorder." (PMID 39122060, 2024). "Persistent blockade of NMDAR in experimental animals recreates the pathologic features of schizophrenia including down regulation of parvalbumin-positive cortical gamma-aminobutyric acid (GABA)ergic neurons, pyramidal neuron dendritic dysgenesis, and reduced spine density." (PMID 37875549, 2024). "In contrast, even in the absence of cellular-level (micro)structural changes, the potential overlap in GABAergic activity in parvalbumin-positive neurons to hippocampal dysfunction in schizophrenia and autism might be relevant to a common pathway." (PMID 37891246, 2024). "Moreover, prolonged oxidative stress in the circuitry of neurotransmitters, e.g., parvalbumin interneurons in GABAergic circuits, have been identified in schizophrenia and bipolar disorder." (PMID 38419903, 2024). "Parvalbumin (PV)-expressing GABAergic interneurons have a crucial role in maintaining the excitation-inhibition balance in the cortex and contribute to the development of psychiatric conditions like autism, schizophrenia or Alzheimer`s disease." (PMID 38310185, 2024).
schizophrenia (continued). "This discovery could significantly advance the GABA hypothesis for clinical applications that rescue the dampened firing of parvalbumin neurons through the modulation of the Kv3.1 channel in patients with schizophrenia." (PMID 39201380, 2024). "The following review gives an update about the role of PNNs for the maturation of parvalbumin-expressing interneurons and summarizes recent findings about the impact of PNNs in different neurological and neuropsychiatric disorders like schizophrenia or epilepsy." (PMID 37143468, 2023). "It has been reported that the glutamatergic neurotransmission via NR2A-containing NMDARs on parvalbumin-expressing interneurons in the cortex may be altered in schizophrenia." (PMID 37143468, 2023). "Therefore, the areas most affected in patients with schizophrenia characteristically show a high density of parvalbumin or somatostatin GABA interneurons, which interestingly both developmentally derive from the medial ganglionic eminence of the subpallium." (PMID 37848404, 2023). "However, the multifactorial pattern of schizophrenia also includes the aberrant function of fast-spiking parvalbumin-positive interneurons (PVIs) which leads to excitatory imbalance." (PMID 36138883, 2022). "Interestingly, studies on postmortem schizophrenia patients unraveled a reduction of somatostatin- and parvalbumin-positive interneurons in the hippocampus, which was furthermore confirmed by qRT-PCR analysis." (PMID 35628292, 2022). "The parvalbumin (PV)-containing subgroup of GABAergic neurons is particularly affected in schizophrenia and animal models of psychosis, including after METH administration, parvalbumin (PVALB) methylation is increased in METH dependence and METH-induced psychosis." (PMID 36091781, 2022). "Research into the cellular and molecular mechanisms controlling the onset and end of these critical periods, notably controlled by the maturation of parvalbumin-expressing basket cells, have brought to light the presence of anomalies in the maturation of these neurons in patients with schizophrenia." (PMID 36590919, 2022). "Interestingly, another current study revealed that a regular physical exercise significantly increased the neurogenesis of parvalbumin-positive interneurons with ameliorating effects for schizophrenia-like phenotypes." (PMID 35628292, 2022). "Because GAD67 reduction was predominantly observed in parvalbumin-positive GABAergic interneurons in the postmortem brains of schizophrenic patients, mice with conditional knockout of GAD67 in parvalbumin-positive cells have been used as an animal model of schizophrenia." (PMID 33413507, 2021). "It was speculated that redox state and NMDAR activity interacted with each other in schizophrenia and these two individual factors both had developmental effects on parvalbumin-expressing GABAergic interneurons in schizophrenia." (PMID 33912003, 2021). "Among the neural substrates affected in schizophrenia, parvalbumin-positive interneurons (PVs), which are fast-spiking, inhibitory interneurons, and perineuronal nets (PNNs), which form part of the extracellular matrix (ECM) that surrounds PVs, both regulate E/I balance in the cortex." (PMID 34681799, 2021). "In particular, reduced parvalbumin expression may impact on prefrontal cortex (PFC) GABAergic interneurons that are known to be decreased in schizophrenia populations." (PMID 34146134, 2021). "However, through animal experiments and clinical studies, a decrease in parvalbumin neurons has been reproducibly observed in hypothyroidism, and this phenomenon has also been observed in the postmortem brains of patients with schizophrenia and autism." (PMID 34955723, 2021). "Deficits of brain parvalbumin (PV) are a consistent finding in schizophrenia." (PMID 34831111, 2021).
schizophrenia (continued). "In addition, in recent years, a decrease in parvalbumin has been observed in the postmortem brains of patients with autism and schizophrenia, reaffirming the importance of thyroid hormone research in these conditions." (PMID 34955723, 2021). "Numerous studies, including postmortem, genetic, and in vivo electrophysiological experiments in murine models of schizophrenia, consider the disruption of parvalbumin- (PV-) positive GABAergic interneurons as a critical pathophysiological mechanism of schizophrenia." (PMID 33552387, 2021). "Also, it was suggested that oxidative stress is the main agent responsible for parvalbumin inhibitory interneurons deficit, which is a linker to schizophrenia." (PMID 34356151, 2021). "In neurodevelopmental disorders (NDDs) including autism spectrum disorder (ASD) and schizophrenia, impairment/malfunctioning of a subpopulation of interneurons expressing the calcium-binding protein parvalbumin (PV) –here termed Pvalb neurons– has gradually emerged as a possible cause." (PMID 33132847, 2020). "The increase in parvalbumin could also reflect a change in the number of certain subpopulations of parvalbumin-positive neurons in the cerebellum in schizophrenia." (PMID 32639965, 2020). "Parvalbumin is expressed in subpopulations of GABAergic interneurons in the brain, which are considered more metabolically and electrically active than the neighbouring neurons and play an important role in the pathophysiology of schizophrenia." (PMID 32639965, 2020). "Future post-mortem work on the molecular differentiation of parvalbumin interneuron subclasses and the regulational factors that act upon them will be needed to determine the true nature of parvalbumin interneuron pathology in schizophrenia." (PMID 31529297, 2019). "Oxidative stress in parvalbumin interneurons is known to play a role in cellular dysfunction in many animal models of neurodevelopmental disorders including Fragile X, Phelan-McDermid, schizophrenia, and 15q13.3 deletion syndromes." (PMID 30635860, 2019). "Interestingly, in many of these disorders, including schizophrenia and autism, the function and/or expression of parvalbumin-expressing (PV+) interneurons in the prefrontal cortex (PFC) is altered." (PMID 30792384, 2019). "In addition, MMP9 is involved in the degradation of the perineuronal net, a type of ECM that wraps fast-spiking parvalbumin interneurons; the perineuronal net is known to be affected in the medial prefrontal brain of schizophrenia patients." (PMID 29875399, 2018). "In combination with findings of altered expression of NMDA receptors within these interneurons, it is well-supported that inhibitory interneurons, particularly those expressing the calcium-binding protein parvalbumin, are a locus for dysfunction in schizophrenia." (PMID 30425662, 2018). "Furthermore, these animal models elicited histological changes in the brain similar to those observed in schizophrenia patients, i.e., decreased numbers of parvalbumin-positive interneurons and dendritic spines of pyramidal neurons in the frontal cortex." (PMID 29515467, 2018). "Network and cognitive deficits associated with neurological disorders, such as schizophrenia, that result from NMDA receptor-hypofunction have been mainly attributed to dysfunction of parvalbumin-expressing interneurons that paradoxically express low levels of synaptic NMDA receptors." (PMID 28751664, 2017). "In our study, besides the changes in parvalbumin expression, the MK-801 treatment increased the expression of astrocytic and microglial cell markers in the mPFC, similar to what has been observed in post-mortem brain of schizophrenia patients." (PMID 28588483, 2017). "Glutamate theories of schizophrenia suggest that the disease is associated with a loss of NMDA receptors, specifically on GABAergic parvalbumin-expressing interneurons (PVIs), leading to changes in the excitation–inhibition balance in the prefrontal cortex (PFC)." (PMID 28819639, 2017).
schizophrenia (continued). "For example, CBD attenuates the decrease in hippocampal neurogenesis and dendrite spines density induced by chronic stress and prevents microglia activation and the decrease in the number of parvalbumin-positive GABA neurons in a pharmacological model of schizophrenia." (PMID 28588483, 2017). "Together, the parvalbumin interneuron myelination hypothesis provides a falsifiable model for guiding future studies of schizophrenia pathophysiology." (PMID 27646261, 2017). "Here, we propose that myelination of fast-spiking parvalbumin (PV) interneurons could be an important locus of pathophysiological convergence in schizophrenia." (PMID 27646261, 2017). "In this Perspective, we hypothesize that previous observations of interneuron dysfunction and myelination abnormalities in schizophrenia might converge on the altered myelination of fast-spiking parvalbumin (PV) interneurons." (PMID 27646261, 2017). "Combination of GABA 1H-MRS or GABA PET/SPECT with electroencephalogram gamma-band oscillations in schizophrenia, which reflect on parvalbumin neuron activity, may help determine whether such GABAergic subgroups of patients are identifiable in vivo." (PMID 28585933, 2017). "These fast-spiking, parvalbumin-expressing interneurons are required for gamma oscillations and impact multiple cognitive functions, both of which are disrupted in schizophrenia patients." (PMID 27432008, 2016). "Parvalbumin-expressing interneurons, including the basket cell network which is fundamental to gamma oscillations, are reduced in number in post mortem studies of bipolar disorder and schizophrenia, and in chronically-stressed adult rats." (PMID 27363787, 2016). "Furthermore, Q-PCR was used to identify any change in expression of PVALB, previously known to be altered in the post-mortem brains of schizophrenia patients, and by isolation rearing in the rat." (PMID 27382048, 2016). "GCLM-KO mice exhibit a significant decrease in γ-frequency synchronized oscillations, a shared feature of schizophrenia and autism, and D4 dopamine receptor activation in parvalbumin-expressing GABAergic interneurons is essential for synchronized γ oscillations." (PMID 26799654, 2016). "Deficits of γ oscillations in schizophrenia have been hypothesized to be related to abnormalities in the function of inhibitory interneurons in the upper cortical layers, particularly the parvalbumin-expressing, fast-spiking class." (PMID 26539128, 2015). "There are significantly decreased levels of GABAergic neuronal markers like parvalbumin mRNA in the prefrontal cortex and in the dorsolateral prefrontal cortex of schizophrenia patients, decreased levels have been reported of glutamic acid decarboxylase (GAD67) mRNA, the GABA-synthesizing enzyme." (PMID 24592242, 2014). "This hypothesis is supported by findings showing decreased functioning of parvalbumin-positive (PV) interneurons in patients with schizophrenia." (PMID 23532620, 2013). "Interestingly, in recent studies experimental evidence for a direct link between the redox imbalance and the development of parvalbumin expressing interneurons has been delivered, an interneuron subtype which has shown to be reduced in schizophrenia." (PMID 23869202, 2013). "In the prefrontal cortex, parvalbumin-positive inhibitory neurons play a prominent role in the neural circuitry that subserves working memory, and alterations in these neurons contribute to the pathophysiology of schizophrenia." (PMID 23950961, 2013). "Interestingly, one of the common findings in both animal models and postmortem tissue from patients with schizophrenia is a reduction of the calcium buffer parvalbumin (PV) mRNA or protein level in cortical fast-spiking (FS) interneurons." (PMID 24027504, 2013).